TFF1 (trefoil factor 1)
Diseases named in the same sentence as TFF1 in open-access papers (continued):
Sharing a sentence is not in itself a finding about the gene and the disease.
breast carcinoma (continued). "Here, we show that MSK1 and MSK2 belong to different multiprotein complexes but both mediate chromatin remodeling that is required at the enhancer and UPE for TPA-induced initiation of TFF1 expression in MCF-7 breast cancer epithelial cells." (PMID 23675462, 2013). "TFF1 protein is known to enhance the migration, invasion, and metastatic potential of breast cancer cells both in vitro and in vivo." (PMID 23675462, 2013). "TFF1 was first discovered in a human breast cancer cell line and later shown to stimulate migration of breast cancer cells." (PMID 24116124, 2013). "The requirement of both MSK1 and MSK2 in the TPA-induction of the TFF1 gene in human breast cancer cells is clearly shown in studies with the MSK inhibitor H89 and in the MSK1 and MSK2 knockdown cells." (PMID 23675462, 2013). "Induction of trefoil factor 1(Tff1), in ER (+) breast cancer T47D cells is a well-established tool to evaluate estrogenic activity of xenobiotics." (PMID 23874474, 2013). "T47D cells induced TFF-1, which had previously been identified to be over-expressed in primary breast cancers that preferentially relapse to the bone." (PMID 22235336, 2012). "MCF-7 breast cancer cells expressing a higher level of TFF1 have an increased capacity to spread by invading surrounding tissues thus conferring them with a more invasive/metastatic phenotype." (PMID 21283680, 2011). "We therefore tested the same TFF1 and GREB1 probes on ERα–positive MCF-7 breast cancer cells, which have also been reported to demonstrate rapid nuclear colocalisation of TFF1 and GREB1 upon E2 addition." (PMID 20421946, 2010). "In human Estrogen Receptor α (ERα)-positive breast cancers, 5′ end dense methylation of the estrogen-regulated pS2/TFF1 gene correlates with its transcriptional inhibition." (PMID 20300195, 2010). "The pS2 gene (also called TFF1) has been identified by differential screening of a cDNA library from the human breast cancer cell line MCF7." (PMID 20300195, 2010). "TFF1 is a small (6.67 kDa) secreted protein identified originally as an oestrogen-regulated mRNA in breast cancer cells." (PMID 18722547, 2009). "TFF1 is generally accepted as one of the most reliable estrogen-responsive biomarker genes for in vitro MCF-7 breast cancer cells." (PMID 16393665, 2006). "Originally, TFF1 was discovered as an estrogen-responsive gene in breast cancer cell lines." (PMID 41898614, 2026). "However, the mechanisms dictating TFF1 transcriptional dynamics and the implications of its expression variability in breast cancer progression remain to be elucidated." (PMID 41000645, 2025). "TFF1 knockdown enhanced anchorage-independent growth in breast cancer cells in vivo and in vitro, reduced apoptosis and induced proliferation in gastric cancer cells, and accelerated the development of esophageal adenocarcinoma and hepatocellular carcinoma in vivo." (PMID 39410561, 2024). "Our data show that TFF1 positivity occurs most commonly in mucinous carcinomas of the ovary, colorectal adenocarcinomas, breast cancer, bilio-pancreatic, and gastro-esophageal adenocarcinomas, neuroendocrine neoplasms, adenocarcinomas of the cervix uteri, and in urothelial neoplasms." (PMID 39410561, 2024). "Similarly, trefoil factor 1 (TFF1), a small secretory protein, demonstrates elevated levels across various cancer types, including breast cancer." (PMID 38250812, 2023). "It was shown that in primary tumours TFF1 expression can modulate the growth of ER+ breast cancer." (PMID 37958607, 2023). "Furthermore, the expressed level of miR-326 is inhibited by circ_0061825, also known as circ_TFF1, resulting in the overexpression of the TFF1 gene in breast cancer." (PMID 36769372, 2023). "Circ-TFF1 was shown to impact breast cancer progression by activating the mir-326/TFF1 axis." (PMID 35577352, 2022).
breast carcinoma (continued). "The CA15-3, CYFRA21-1, and TFF1 levels were significantly different among the breast cancer group, benign group, and control group (33.81 ± 12.46 vs 19.02 ± 6.47 vs 9.55 ± 2.64, 4.08 ± 1.41 vs 1.96 ± 1.19 vs 0.99 ± 0.21, 1.39 ± 0.54 vs 1.04 ± 0.26 vs 0.89 ± 0.12, P < 0.05)." (PMID 35392152, 2022). "TFF1, trefoil factor 1, is cloned from the breast cancer cell line MCF-7." (PMID 35692369, 2022). "In addition to the mentioned circRNAs, it has been shown that circ‐TFF1 (hsa_circ_0061825) and circEPSTI1 also are involved in the apoptosis of breast cancer cells through sponging miRNAs." (PMID 34400888, 2021). "TFF1 was recently reported to inhibit cell growth, migration, and invasion of breast cells in vitro and has also been suggested to be a prognostic biomarker for breast cancer." (PMID 33435254, 2021). "Breast cancer groups bearing germline and somatic BRCA2 mutations as well as non-mutated patients were characterized by the upregulation of luminal subtype signatures such as ESR1, TFF1, TFF2." (PMID 33525353, 2021). "Next, the function role of circ‐TFF1 in breast cancer was inquired." (PMID 31961997, 2020). "Furthermore, TFF1 expression occurs in certain premalignant conditions as well as in various tumors, and TFF1 is used as a prognostic marker, particularly for breast cancer." (PMID 32260357, 2020). "Importantly, we discovered that the level of circ‐TFF1 was heightened along with the progression of breast cancer." (PMID 31961997, 2020). "Next, loss‐of‐function assays were implemented to disclose the role of circ‐TFF1 in breast cancer." (PMID 31961997, 2020). "Furthermore, rescue and in vivo experiments revealed that circ‐TFF1 targets miR‐326 to enhance TFF1 expression for the cellular activities of breast cancer." (PMID 31961997, 2020). "Collectively, circ‐TFF1 sponged miR‐326 to regulate TFF1 expression in breast cancer." (PMID 31961997, 2020). "Subsequently, we detected circ‐TFF1 expression in 58 pairs of clinical tissues and results demonstrated the expression pattern of circ‐TFF1 in healthy tissues, para‐carcinoma tissues and breast cancer samples are low, middle, high." (PMID 31961997, 2020). "Additionally, it was uncovered that silencing of circ‐TFF1 inhibited TFF1 expression while promoted the level of miR‐326 in two breast cancer cells." (PMID 31961997, 2020). "Prest also pointed out that TFF1 can promote breast cancer cell migration." (PMID 31874629, 2019). "Serum TFF1 had positive correlation with expression of TFF1 in breast cancer tissue." (PMID 28687783, 2017). "Furthermore, LSD1 knockdown in breast cancer cells blocked the estrogen-mediated transcription of TFF1 and GREB1 by inhibiting the interaction between the TFF1 and GREB1 loci and the interchromatin granules containing transcription-related factors." (PMID 28811844, 2017). "Overall, 26 out of 46 (56.5%) breast cancer was positive for TFF1." (PMID 28687783, 2017). "In normal epithelial tissue surrounding breast cancer, 4 (8.7%) patients were positive for TFF1." (PMID 28687783, 2017). "However, a recent study of breast cancer patients found that TFF1 expression was greater for ER/PR positive breast cancers, which generally have a better prognosis than ER/PR negative breast cancers." (PMID 26510686, 2015). "Since TFF1 is strictly controlled by the E2/ERα complex, it provides a good measure of estrogen signaling in breast cancer cells and a preliminary clinical study reported a parallel relationship between the TFF1 high expression levels and the proliferation of breast cancer cells." (PMID 25070479, 2014). "Transcription of TFF1 is commonly used to evaluate the estrogenic activity in human breast cancers." (PMID 24349450, 2013). "The dose response curve of TFF1 inducing breast cancer cell movement shows a clear bell shape." (PMID 23936323, 2013). "TFF1 (pS2) is one of the best characterized estrogen-responsive genes in breast cancer." (PMID 17555561, 2007).
breast carcinoma (continued). "Thus, considerable controversy exists about the role of TFF1 in breast cancer." (PMID 39583845, 2024). "In addition to CA15-3 and CYFRA21-1, TFF1 is also closely related to breast cancer." (PMID 35392152, 2022). "In addition, circ‐TFF1 was prevailingly seated in the cytoplasm of breast cancer cells." (PMID 31961997, 2020). "Based on this result, elevated serum TFF1 may originate directly from breast cancers." (PMID 28687783, 2017). "Therefore, the mechanism of MSK-mediated TFF1 gene transcription in breast cancer may hold important insights into breast cancer progression and merits further study." (PMID 23675462, 2013). "The results indicated a positive correlation between PSMD14 and several ERα target genes, including GREB1, TFF1, and MCM6, in breast cancer samples." (PMID 38017133, 2024). "Genes with reduced expression in the dataset that were common to metastatic breast cancer and brain tumours included, for example, the cell line invasion markers JUN, MMP3, TFF1 and HAS2." (PMID 37958607, 2023). "In breast cancer T47D and MCF-7 cells, FOXD3-AS1 cleared the expression of miR-363 and upregulated TFF1 expression and PI3K/Akt signaling, leading to cell proliferation." (PMID 35280790, 2022). "For example, circ0061825 was reported to regulate breast cancer progression and EMT by sponging miR-326 and targeting TFF1; circ0002178 sponged miR-328-3p to regulate cellular viability, metabolism and angiogenesis in breast cancer." (PMID 35383130, 2022). "Studies have found that TFF1, one of the downregulated genes in the A3Bhigh group, was regulated by APOBEC3B in breast cancers." (PMID 36249021, 2022). "Within this group of selected genes, we found the family of trefoil factor secreted peptides TFF1, TFF2 and TFF3, which are known to characterize luminal breast cancers." (PMID 35216615, 2022). "The result showed that the protein expression of TUBB3, MCM2, FN1, S100A7, and TFF1 was increased, and the protein expression of MYOC was downregulated in luminal A breast cancer, which was consistent with the result of RNA expression." (PMID 35692369, 2022). "As a result of our algorithm, we identified a signature of 5 CTC-specific genes, i.e., ADPRHL1, ELF3, FCF1, TFF1 and TFF3, and explored its clinical significance according to their expression in CTC-enriched blood samples in our breast cancer case series." (PMID 35216615, 2022). "The protein expression results of TUBB3, MCM2, MYOC, FN1, S100A7, and TFF1 were consistent with the mRNA expression result COL10A1, LEP, PLIN1, PGM5-AS1, and TRHDE-AD1 were capable of discriminating luminal A breast cancer and normal controls." (PMID 35692369, 2022). "TFF1 and TFF3 overlapped frequently among the top 200 genes for breast cancer cell lines and 8 cancer drugs used in our study." (PMID 34693378, 2021). "When we applied heteroDE to breast cancer samples, we identified 7 cfRNA biomarkers (SCGB2A2, CASP14, FABP7, CRABP2, VGLL1, SERPINB5, TFF1), 3 of which (FABP7, SCGB2A2, CASP14) overlap with previously identified DCB genes." (PMID 33883548, 2021). "Furthermore, the results of FISH assay illuminated that circ‐TFF1 was principally expressed in the cytoplasm of two breast cancer cells, which was also affirmed by analysing its expression in the cytoplasm and nucleus of breast cancer cells after subcellular fractionation." (PMID 31961997, 2020). "We next examined the expression of three estrogen-responsive genes in these two cell lines; namely Growth Regulation By Estrogen In Breast Cancer 1 (GREB1), Cyclin D1 (CCND1) and Trefoil Factor 1 (TTF1)." (PMID 30370249, 2018). "The higher levels of TFF1 and TFF3 mRNA in CTCs of some metastatic breast cancer patients confirmed that they act as tumor progression factors." (PMID 29977293, 2018). "We next examined the correlations between serum TFF1 and TFF3 levels and expression of TFF1 and TFF3 in breast cancer." (PMID 28687783, 2017).
breast carcinoma (continued). "Serum TFF1 and TFF3 were significantly higher and serum TFF2 was significantly lower in breast cancer patients." (PMID 28687783, 2017). "Serum TFF1 and TFF3 levels in breast cancer patients were significantly higher than in the healthy individuals." (PMID 28687783, 2017). "Serum TFF1, TFF2, and TFF3 in 94 breast cancer patients and 84 healthy individuals were measured and compared." (PMID 28687783, 2017). "Immunohistochemical staining (IHC) for TFF1, TFF2, and TFF3 was performed for breast cancer tissue and normal epithelial tissue surrounding breast cancer." (PMID 28687783, 2017). "At that time, high serum TFF1 and low TFF2 can be used for more refining of breast cancer patients for the imaging examination." (PMID 28687783, 2017). "In this report, AUC of combination of serum TFF1, TFF2, and TFF3 is 0.96 suggesting that combined testing for TFF1, TFF2, and TFF3 can provide a powerful tool for breast cancer screening." (PMID 28687783, 2017). "And denying the tumor volume in analyzing correlation between TFF1, TFF2, and TFF3 expressions in breast cancer tissue and serum TFF1, TFF2, and TFF3 is also a limitation." (PMID 28687783, 2017). "For evaluation of the serum TFF1, TFF2, and TFF3 for cancer screening, serum of 22 breast cancer patients before treatment were evaluated." (PMID 28687783, 2017). "Immunohistochemical staining for TFF1 was positive in 56.5% of breast cancer tissues and TFF3 was positive in 73.9% of breast cancer tissues." (PMID 28687783, 2017). "TFF1, TFF2, and TFF3 values were all statistically different between breast cancer patients and healthy individuals." (PMID 28687783, 2017). "Serum TFF1 and TFF3 levels in breast cancer patients were significantly higher than in healthy individuals." (PMID 28687783, 2017). "Serum screening with TFF1, TFF2, and TFF3 for breast cancer can increase the screening receiving rate." (PMID 28687783, 2017). "The positive rate of TFF1 and TFF3 in invasive lobular carcinoma, ductal carcinoma in situ (DCIS), and lobular carcinoma in situ (LCIS) was reported to be higher than in invasive ductal carcinoma." (PMID 28687783, 2017). "In the present study, we evaluated the effect of BPAF on endogenous transcription of TFF1, GREB1 and CTSD in human breast cancer cells." (PMID 24727858, 2014). "The gene cluster included TFF1, PGR, GREB1, and other ER-sensitive genes such as insulin-like growth factor binding protein 1 (IGFBP1), breast carcinoma amplified sequence, and fibulin." (PMID 23938070, 2013). "TFF1 is an ESR1 regulated protein, and it has been found to enhance cell migration and oncogenicity in breast cancers." (PMID 23320390, 2012). "It has been shown that TFF1 (also known as pS2) stimulates the movement of MCF-7 and other breast cancer cells and promotes their dissemination by preventing anoikis." (PMID 21283680, 2011). "TFF1, AGR2 and SBEM were expressed to a varying degree in all breast cancer cell lines, but also in other malignancies." (PMID 21816090, 2011). "The most significant ones include TFF1, CCND1, IGFBP4, C3, ADORA1, GREB1, and MYC, which have been shown by candidate gene analysis to be estrogen regulated genes in breast cancer cell lines." (PMID 21878096, 2011). "The computational pipeline was applied to a panel of 45 breast cancer cell lines, and the protocol identified a list of 58 genes, including COL1A2, TOP2A, TFF1, and VAV3, whose key roles in epigenetic regulation are consistent with known literature." (PMID 20525369, 2010). "Given this potential discrepancy, we sought to re-examine the nuclear organisation of TFF1 and GREB1 upon E2 stimulation in normal-like MCF10A and cancerous MCF-7 breast cancer cell lines and in primary HMECs." (PMID 20421946, 2010). "As expected, this list contains numerous markers of breast cancer cells whose expression specificity was previously reported by other (notably ERBB3, XBP1, KRT18, IL6ST, CREB1, TFF1, TFF3)." (PMID 19104654, 2008).
breast carcinoma (continued). "This cohort contained a subset of genes that could be considered potential biomarkers for breast cancer progression, including FOXA1, MLPH, ESR1, AR, GATA3, TFF1, THSD4, and TBC1D9." (PMID 38020889, 2023). "In breast cancer, estrogen receptor 1 (ESR1) regulates the TFF1 expression." (PMID 37037466, 2023). "The results indicated that except for TFF1 (AUC = 0.774), COL10A1 (AUC = 1.000), LEP (AUC = 0.984), PLIN1 (AUC = 0.966), PGM5-AS1 (AUC = 0.969), and TRHDE-AD1 (AUC = 1.000) were capable of discriminating luminal A breast cancer and normal controls." (PMID 35692369, 2022). "In addition, FOXD3-AS1 has been reported to enhance tamoxifen (TMX) resistance in breast cancer T47D and MCF7 cells through the microRNA-363/TFF1/PI3K/Akt signaling pathway." (PMID 35280790, 2022). "Finally, we analyzed the results of the combined analysis of TFF1 and TFF3 in the blood of breast cancer patients." (PMID 29977293, 2018). "The use of TFF1 and TFF3 as markers in the CTCs of breast cancer patients is hopeful." (PMID 29977293, 2018). "The serum TFF1 in patients with immunohistologically positive for TFF1 in breast cancer was significantly higher than patients with immunohistologically negative for TFF1." (PMID 28687783, 2017). "In this study, we have analyzed whether serum TFF1, TFF2, and TFF3 can be biomarkers of breast cancer." (PMID 28687783, 2017). "We have analyzed serum TFF1, TFF2, and TFF3 as screening biomarkers for breast cancer." (PMID 28687783, 2017). "TFF1 and TFF3 have an estrogen responsive element, and bad prognosis of TFF1 and/or TFF3 positive breast cancer may be masked by good prognosis of ER+ breast cancer." (PMID 28687783, 2017). "In summary, this study has demonstrated that the serum TFF1, TFF2, and TFF3 could be effective markers for breast cancer screening." (PMID 28687783, 2017). "0.72, and the order of accuracy for breast cancer patient screening was TFF2, TFF3 and TFF1." (PMID 28687783, 2017). "Serum TFF1 of histologically TFF1 positive breast cancer patients was 1.74 ± 0.26 ng/ml, and that of histologically TFF1 negative breast cancer patients was 0.88 ± 0.23 ng/ml." (PMID 28687783, 2017). "Recently, a study reported an association between serum levels of estradiol and gene expression of trefoil factor 1 (TFF1), growth regulation by estrogen in breast cancer 1 (GREB1), PDZ domain containing 1 (PDZK1) and progesterone receptor (PGR) in ER+ breast carcinomas." (PMID 21812955, 2011). "Furthermore, the results from our WGCNA analysis indicated the existence of unknown networks between INO80 and a subset of luminal breast cancer biomarkers, including FOXA1, ESR1, GATA3, TFF1, and AR." (PMID 38020889, 2023). "Additionally, breast cancer patients with a positive ER expressed TFF1 higher than those who were negative for ER." (PMID 36836779, 2023). "While knockdown of circ-TFF1 impaired the migration and EMT processes of breast cancer cells, stimulation enhanced its inhibitory effect on mir-326, reducing mir-326, accelerating tumor cell growth, increasing EMT processes, and promoting breast cancer development and progression." (PMID 35577352, 2022). "Because the importance of the regulation of TFF3 by oestrogen in breast cancer is unknown, unlike that of TFF1, it was studied further." (PMID 25900183, 2015). "Previously, we reported that TPA addition to MCF-7 breast cancer cells cultured under estrogen-free serum starved conditions resulted in the recruitment of MSK1 to the TFF1 UPE, along with increased H3S10ph (but not H3S28ph) and H3 acetylation (H3K9acK14ac) levels." (PMID 23675462, 2013). "In the past, TFF3 - and TFF1, but not TFF2 - mRNA was detected in breast tumors and estrogen-responsive breast cancer cell lines and TFF3 was ranked among genes down-regulated in MDA-MB-231 compared to MCF7 cells." (PMID 35216615, 2022).